MUC1 (mucin 1, cell surface associated)
Diseases named in the same sentence as MUC1 in open-access papers (continued):
Sharing a sentence is not in itself a finding about the gene and the disease.
immune dysfunction (3 papers, 2023). "Unlike MUC1, IL-22 also regulates MUC13 expression via p38 MAPK activation, a signaling pathway involved in TLR4-mediated cell proliferation and immune dysfunction in IBD." (PMID 37174625, 2023).
cardiovascular disease (2 papers, 2020 to 2023). "Additionally, some of the predicted genes, including BCL6, LDB3, MUC1 and SYNC, have been implicated in other cardiovascular diseases." (PMID 38100461, 2023).
blood cancers (1 paper, 2022). "Although CAR-T therapies were mainly provided to be effective in blood cancers rather than solid tumors, the CAR-T therapy of MUC1 for SBA may be developed and further studied to benefit SBA patients." (PMID 36104333, 2022).
Gynecologic Tumors (1 paper, 2014). "We asked here whether the gynecologic tumors in MUC1KrasPten mice that express MUC1 antigen as self also trigger MUC1-specific humoral immunity." (PMID 25078979, 2014).
MUC1 also shares sentences with these, for which no sentence is quoted: idiopathic pulmonary fibrosis (62 papers); connective tissue disease (21); acute respiratory distress syndrome (19); fibrosis (19); pneumonitis (19); systemic sclerosis (12); idiopathic interstitial pneumonia (11); radiation pneumonitis (11); rheumatoid arthritis (10); respiratory failure (9); synovial sarcoma (9); dermatomyositis (8); neurofibroma (8); pulmonary alveolar proteinosis (8); bacterial pneumonia (7); breast (7); Interstitial pneumonitis (7); emphysema (6); myositis (6); schwannoma (6); anemia (5); Ewing sarcoma (5); mucinous adenocarcinoma (5); perineurioma (5); polymyositis (5); pulmonary sarcoidosis (5); sarcomatoid carcinoma (5); brain tumor (4); bronchiectasis (4); bronchopulmonary dysplasia (4).
A further 277 diseases each share a sentence with MUC1 in 4 papers or fewer.